MMP11 (matrix metallopeptidase 11)
Diseases named in the same sentence as MMP11 in open-access papers (continued):
Sharing a sentence is not in itself a finding about the gene and the disease.
breast carcinoma (continued). "Unlike the responses in breast cancer cell lines with high MMP-11 expression, the therapeutic responses in patients with breast cancer may be highly heterogeneous and affected by various microenvironments and immune components, which could have effects on clinical applications." (PMID 34038440, 2021). "Our findings identify the negative correlation of MMP11 and HPSE2 in breast cancer progression, which provides novel insight into the optimization of breast cancer treatment." (PMID 26084486, 2015). "Importantly, we found that the gene expression of MMP11 and CD2 are independent prognostic factors for DMFS in HR−/HER2+ breast cancer, whereas clinical variables were not significant prognostic indicators." (PMID 28409241, 2017). "However, the close relationship between MMP11 and HPSE2 has not been reported, which brings new insight into the breast cancer field." (PMID 26084486, 2015).
gastric cancer (37 papers, 2007 to 2025). A primary or metastatic malignant neoplasm involving the stomach. "In gastric cancer, MMP11+ mCAFs were primarily associated with COL11A+ CAFs, with a secondary association to CXCL5+ CAFs." (PMID 40552583, 2025). "MMP11 is significantly expressed in gastric cancer cells and has been implicated in enhancing tumor growth and invasion through the modulation of IGF-1 signaling." (PMID 39895782, 2025). "Of clinical significance, MMP11 is overexpressed in exosomes purified from plasma of gastric cancer patients and tumor tissues, and associated with overall survival of gastric cancer patients." (PMID 31595150, 2019). "Our findings reveal the regulation of MMP11 by exosomal miR-139 in CAFs associated with gastric cancer progression." (PMID 31595150, 2019). "High plasma levels of MMP-11 were found to be associated with lymph node metastasis and prognosis in patients with gastric cancer, especially advanced carcinoma." (PMID 25423087, 2014). "Moreover, MMP11 is overexpressed in exosomes purified from plasma of gastric cancer patients and tumor tissues and associated with overall survival of gastric patients." (PMID 31595150, 2019). "In terms of gastric cancer, PrPc was highly expressed in metastatic gastric cancer, contributing to cancer invasion via ERK1/2 pathway and is associated with increased expression of MMP11 at both mRNA and protein levels." (PMID 39972491, 2025). "Exosome miR-139 secreted by gastric cancer CAFs has been shown to inhibit gastric cancer progression and metastasis by reducing MMP11 in the TME57." (PMID 39895782, 2025). "For example, CAFs marker matrix metalloproteinase 11 (MMP11) can be delivered into gastric cancer cells to promote migration." (PMID 37065499, 2023). "Increased expression of MMP-11 is found in both gastric cancer cells and tumor stromal cells, and it plays a significant role in cancer cell invasion and metastasis." (PMID 36010928, 2022). "In addition, MMP11 in exosomes secreted from gastric cancer-associated fibroblasts can be delivered into GC cells to partially accelerate their progression and metastasis." (PMID 36685842, 2022). "The researchers attempted to shuttle miR-139 into CAFs to increase their bioavailability to gastric cancer cell lines in vitro and to stomach tumors in vivo, and found that both experiments resulted in drastic decreases in MMP11 expression." (PMID 34680611, 2021). "A recent study revealed that exosomal miR-139 from CAFs was able to repress the progression of gastric cancer by inhibiting matrix metalloproteinase 11 (MMP11)." (PMID 34680611, 2021). "MMP11, as a key regulator of extracellular matrix degradation, is negatively regulated by exosomal miR-139 derived from the CAFs of gastric cancer and contributes to gastric cancer cell migration." (PMID 34202583, 2021). "In gastric cancer, an increase in MMP11 in CAF exosomes induces the migration and metastasis of cancer cells, while CAF-derived exosomal miR-139 negatively regulates the level of MMP11." (PMID 33213510, 2020). "Exosomal miR-139 inhibits tumor growth and metastasis of gastric cancer cells by decreasing the expression of MMP11 in vitro and in vivo." (PMID 31595150, 2019). "Here we show that matrix metalloproteinase 11 (MMP11) in exosomes secreted from CAFs can be delivered into gastric cancer cells." (PMID 31595150, 2019). "In this study, we identify that gastric CAFs promote gastric cancer cell migration partially through exosomal MMP11." (PMID 31595150, 2019). "All these results indicated that gastric CAFs promoted gastric cancer cell migration partially through exosomal MMP11." (PMID 31595150, 2019). "MMP11 was overexpressed in numerous types of human carcinoma, including breast, non-small cell lung, gastric cancer, colorectal carcinomas and prostate cancer." (PMID 27323416, 2016). "It is well known that MMP11 is overexpressed in several human cancers, including breast, cervix, colon, ovary, prostate, and stomach cancers." (PMID 22574217, 2012).
gastric cancer (continued). "Cox multivariate regression analysis demonstrated that the serum level of MMP-11 was an independent prognostic factor for patients presenting with advanced gastric carcinoma." (PMID 21513571, 2011). "For example, inhibition of MMP11 can impede the metastasis of gastric cancer." (PMID 33836753, 2021). "The data from this study indicated that miR-139 produced in gastric CAFs may repress the progression and development of gastric cancer metastasis by modulating the level of MMP11 in the surrounding tumor microenvironment." (PMID 34680611, 2021). "Knockdown of MMP11 inhibits proliferation and invasion of gastric cancer cells." (PMID 31992202, 2020). "We also find that MMP11 is negatively regulated by exosomal miR-139 in the CAFs of gastric cancer." (PMID 31595150, 2019). "Gastric CAFs promote gastric cancer cell migration partially through exosomal MMP11." (PMID 31595150, 2019). "Our findings indicate that exosomal miR-139 derived from gastric CAFs could inhibit the progression and metastasis of gastric cancer by targeting MMP11 in TME." (PMID 31595150, 2019). "The aim of the present study was to investigate whether elevated MMP-11 expression could predict responses to front-line chemotherapy and prognosis of Chinese patients with advanced gastric carcinoma." (PMID 21513571, 2011). "Besides TGF-β signaling, the insulin-like growth factor (IGF) signal transduction cascade is crucially involved in EMT in gastric cancer, where MMP11 knockdown was able to diminish IGF1 signaling and concomitantly reduced the invasive potential of gastric cancer cells." (PMID 35269560, 2022). "Thus, we propose that exosomal miR-139 derived from gastric CAFs could inhibit the progression and metastasis of gastric cancer by decreasing MMP11 in tumor microenvironment." (PMID 31595150, 2019). "Overexpression of MMP11 could promote invasion of gastric cancer cells." (PMID 27323416, 2016). "Textural features of AGC on FDG PET/CT showed significant correlations with the histopathological classification, Lauren classification, pN stage of gastric cancer, CD8 T lymphocyte and macrophage infiltrations, and MMP-11 expression in the tumor tissue." (PMID 36010928, 2022). "In gastric cancer, CTBP1-AS2 promotes cells proliferation and metastasis and suppresses apoptosis by regulating the miR-139-3p/MMP11 axis." (PMID 35039872, 2022). "Conversely, Snail overexpression increased invasion and migration of gastric cancer cells, in line with increased VEGF and MMP11." (PMID 23151184, 2012). "In conclusion, we showed that a combination of expression of PDGFRB, INHBA, MMP11, and galectin-10 in GC tissues may serve as a useful biomarker for survival stratification in patients with pStage II/III gastric cancer following curative resection." (PMID 36139587, 2022). "While the increased expression of PrPC in metastatic gastric cancer cells can endorse the invasion and metastasis by activating the mitogen-activated protein kinases (MEK)/ERK pathway, which leads to matrix metalloproteinase-11 transactivation (MMP11)." (PMID 36359353, 2022). "In gastric cancer, miR-30a-3p mediates cancer cell invasion via STAT3/MMP11 signaling." (PMID 34182542, 2021). "Notably, KISS1, TIMP2, MMP11, IGFBP1, and EGFR have been reported to be involved in the metastasis of gastric cancer." (PMID 32117443, 2020). "MMP11+RRM2 are up-regulated in lung cancer, pancreatic cancer and stomach cancer tissues, and hence may also make a good marker for these three cancer types." (PMID 21060876, 2010).
gastric cancer (continued). "PrPC is highly expressed in metastatic gastric cancer cells and it may promote invasion and metastasis through activation of the mitogen-activated protein kinases (MEK)/ERK pathway and consequent transactivation of matrix metalloproteinase-11(MMP11)." (PMID 34595121, 2021).
prostate carcinoma (25 papers, 2010 to 2025). A carcinoma that arises from epithelial cells of the prostate gland. "Five single-nucleotide polymorphisms (SNPs) of the MMP-11 were analyzed in 578 patients with prostate cancer through real-time polymerase chain reaction analysis." (PMID 33228130, 2020). "In this study, we examined the associations of MMP-11 polymorphisms with the clinicopathological characteristics and biochemical recurrence of prostate cancer." (PMID 33228130, 2020). "In prostate cancer, miR-135a repressed cell migration and proliferation by downregulating matrix metallopeptidase 11 (MMP11), rho associated coiled-coil containing protein kinase 1 (ROCK1), ROCK2, RB associated KRAB zinc finger (RBAK) and STAT643,60,64." (PMID 32944391, 2020). "This study investigated the association of MMP-11 polymorphisms with the clinicopathological characteristics and biochemical recurrence of prostate cancer." (PMID 33228130, 2020). "We further analyzed the genotype distributions of MMP-11 polymorphisms in patients with prostate cancer." (PMID 33228130, 2020). "A previous study suggested that prostate cancers with high expression levels of MMP-11 were significantly associated with a higher probability of biochemical recurrence." (PMID 33228130, 2020). "In conclusion, our results demonstrate that the MMP-11 polymorphisms, particularly rs131451, were associated with tumor development in prostate cancer patients with biochemical recurrence." (PMID 33228130, 2020). "Matrix Metalloprotease 11 (MMP11) expression has been associated with poor prognosis for several cancer types, including breast and prostate cancer." (PMID 24564996, 2014). "With regard to outcome from patients with prostate carcinomas, our results showed a significant association between score values of MMP-11 or -13 and biochemical recurrence." (PMID 20160732, 2010). "In this study, we analyzed five MMP-11 gene polymorphisms (rs131451, rs738791, rs2267029, rs738792, and rs28382575) to elucidate their relationships with the clinicopathological characteristics and biochemical recurrence of prostate cancer." (PMID 33228130, 2020). "A study conducted in Thailand revealed that MMP-11 overexpression was significantly associated with poor survival and that it could potentially be used to predict poor prognosis in prostate cancer." (PMID 33228130, 2020). "However, the impact of MMP-11 polymorphisms on the risk and prognosis of prostate cancer remains poorly investigated." (PMID 33228130, 2020). "Taken together, these findings indicate that MMP-11 rs131451 polymorphisms might be involved in the effect of MMP-11 overexpression on both biochemical recurrence and poor prognosis in patients with prostate cancer." (PMID 33228130, 2020). "Thus, the MMP-11 rs131451 “TC + CC” polymorphic variant may play a role in the development or regulation of biochemical recurrence in prostate cancer." (PMID 33228130, 2020). "Immunohistochemical results from the Human Protein Atlas (HPA) database suggested decreased protein expression levels of CD38 in prostate cancer tissues, while MMP11 and PLK1 showed moderate expression in both normal and cancerous tissues." (PMID 41415207, 2025). "qRT-PCR and Western blot analyses demonstrated elevated MMP11 mRNA and protein levels in prostate cancer (PCa) cell lines (DU145, PC3, 22RV1) compared to normal prostate epithelial cells (RWPE-1)." (PMID 40607407, 2025). "MMP-11 can be considered a potential tumor marker and therapeutic target for advanced prostate cancer." (PMID 39247608, 2024). "MiR-466 targets RUNX2 and, therefore, leads to a suppression of RUNX2-related gene expression, such as AKT, OPN, matrix metalloproteinase-11 (MMP11) in prostate cancer cells." (PMID 34064589, 2021). "We further analyzed the distribution frequencies of the clinicopathological characteristics and MMP-11 genotypic frequencies in prostate cancer patients with biochemical recurrence." (PMID 33228130, 2020).
prostate carcinoma (continued). "Meanwhile, we found the mRNA levels of RBAK and MMP11 significantly increased (P < 0.001) in metastatic prostate cancers and local prostate cancers compared to normal prostate tissues by analyzing GSE6919 database." (PMID 27323416, 2016). "Next, the expression levels of miR-135a, RBAK and MMP11 were further examined in 10 normal prostate tissues and 13 prostate cancers with real-time PCR." (PMID 27323416, 2016). "To evaluate possible prognostic value of miR-135a, RBAK and MMP11, we analyzed RNAseq data from TCGA, a cohort of 52 normal prostate tissues and 419 prostate cancer samples." (PMID 27323416, 2016). "Circulating MMP11 protein as well as the spontaneous immune responses against MMP11 were analyzed in a set of breast and prostate cancer patients." (PMID 24564996, 2014). "Our data show that MMP11 is indeed overexpressed in a subset of breast and prostate cancer patients." (PMID 24564996, 2014). "Our results showed that the global expression of MMP-11 and -13 by prostate carcinomas correlated with higher incidence rate of biochemical relapse." (PMID 20160732, 2010). "In addition, androgen-induced miR-135 regulates prostate cancer apoptosis through suppression of the RB-associated KRAB zinc finger (RBAK) and limits prostate cancer migration through the downregulation of matrix metalloproteinase 11 (MMP11)." (PMID 39273446, 2024). "MMP-11 is a potential tumour marker and therapeutic target for advanced prostate cancer." (PMID 38911387, 2024). "Furthermore, it was previously shown that MMP11 upregulation is correlated to a poor prognosis of prostate cancer, and it is highly expressed in bone metastasis." (PMID 36552843, 2022). "Although the impact of MMP-11 rs131451 on biochemical recurrence was low, previous research suggested that MMP-11 overexpression was associated with poor survival in patients with prostate cancer." (PMID 33228130, 2020). "The MMP-11 SNP rs131451 may contribute to tumor development in prostate cancer patients with biochemical recurrence." (PMID 33228130, 2020). "Furthermore, we used data from The Cancer Genome Atlas (TCGA) to analyze the relationship between MMP-11 mRNA expression levels and prostate cancer carcinogenesis, clinicopathological characteristics, and biochemical recurrence." (PMID 33228130, 2020). "MMP11 expression was determined by immunoistochemistry in breast and prostate cancer samples." (PMID 24564996, 2014). "The MMP-11 SNPs were found to be associated with increased risk of cancer progression and development, metastasis, recurrence, or poor prognosis in many cancers including oral squamous cell carcinoma (OSCC), hepatocellular carcinoma (HCC), prostate cancer, and urothelial cell carcinoma (UCC)." (PMID 35885589, 2022). "Thus, the MMP-11 SNP rs131451 may contribute to the tumor development in prostate cancer patients with biochemical recurrence." (PMID 33228130, 2020). "Likewise, our data led us to consider that MMP-13 and/or MMP-11 may be optimal therapeutic targets for inhibition in prostate carcinoma." (PMID 20160732, 2010). "Therefore, the global expression of MMP-11 and -13 by prostate carcinomas may, in combination with other factors, support useful prognostic information for a more optimal follow-up and treatment from these patients." (PMID 20160732, 2010). "Although MMP11 remains our primary focus based on previous studies, the critical role of CD38 in prostate cancer development warrants concurrent investigation." (PMID 41001131, 2025). "One of the limitations of this study is the lack of tumor specimens from or information about MMP-11 expression levels in patients with prostate cancer." (PMID 33228130, 2020). "We then evaluated miR-135a, RBAK and MMP11 expression level in the noncancerous prostatic cells WPMY-1 and four prostate cancer cell lines LNCaP, 22Rv1, DU145 and PC-3." (PMID 27323416, 2016).
hepatocellular carcinoma (20 papers, 2012 to 2023). A malignant tumor that arises from hepatocytes. "In hepatocellular carcinoma cells, ectopic expression of miR-125a resulted in inhibition of proliferation and metastases, caused by miR-125a's ability to target matrix metalloproteinase 11 (MMP11) and vascular endothelial growth factor A." (PMID 25594017, 2014). "In hepatocellular carcinoma tissues, miR-125a was expressed ectopically and negatively correlated with MMP11 and VEGF-A expression." (PMID 36101746, 2022). "Genetic polymorphisms in MMP-11 have been reported in several types of cancer, including oral squamous cell carcinoma (OSCC), breast cancer, hepatocellular carcinoma (HCC), uterine cervical cancer, and urothelial cell carcinoma." (PMID 33228130, 2020). "In hepatocellular carcinoma, inhibiting miR-125a-5p increases mmp11 and vegfa protein expression, while restoring miR-125a-5p function inhibits proliferation and metastasis." (PMID 25504437, 2015). "Interestingly, mir-125a-5p was shown to reduce the expression of VEGF and MMP11 in hepatocellular carcinoma cells." (PMID 25059272, 2014). "Further, in hepatocellular carcinoma, upregulation of miR-125a significantly repressed the expression of vascular endothelial growth factor A (VEGF-A) and matrix metalloproteinase 11 (MMP11), both in vitro and in vivo." (PMID 25093848, 2014). "In addition, several studies reported the prognostic value of MMPs in cancer, such as MMP11 in PC, MMP2 in hepatocellular carcinoma, MMP1 in cervical squamous cell carcinoma, and so on." (PMID 33761734, 2021). "In hepatocellular carcinoma (HCC) and breast cancer, CD147 increases multi-drug resistance-1 and MMP-11 expression." (PMID 27363028, 2016).